RNU2-4P (RNA, U2 small nuclear 4, pseudogene)
Synonyms: U2; U2/7; RNU2P2
Gene: Small nuclear RNA gene on chromosome 17 (43,387,226 to 43,387,417, reverse strand). Ensembl gene ENSG00000277084.
Homologues: Orthologues: chimpanzee U2 (99% identical), pig U2 (85% identical), dog U2 (81% identical), rat LOC120095786 (81% identical), rabbit U2 (46% identical). Paralogues in human: U2 (93% identical), U2 (90% identical), RNU2-2 (90% identical), RNU2-3P (86% identical), RNU2-52P (86% identical), RNU2-59P (86% identical), RNU2-26P (85% identical), RNU2-6P (85% identical), RNU2-17P (84% identical), RNU2-57P (84% identical), RNU2-48P (83% identical), RNU2-5P (83% identical), and 66 more.